TRIM7 (tripartite motif containing 7)
Description:
E3 ubiquitin-protein ligase that have both tumor-promoting and tumor-suppressing activities and functions in several biological processes including innate immunity, regulation of ferroptosis as well as cell proliferation and migration. Acts as an antiviral effector against multiple viruses by targeting specific viral proteins for ubiquitination and degradation including norovirus NTPase protein or SARS-CoV-2 NSP5 and NSP8 proteins. Mechanistically, recognizes the C-terminal glutamine-containing motif usually generated by viral proteases that process the polyproteins and trigger their ubiquitination and subsequent degradation. Mediates 'Lys-63'-linked polyubiquitination and stabilization of the JUN coactivator RNF187 in response to growth factor signaling via the MEK/ERK pathway, thereby regulating JUN transactivation and cellular proliferation. Promotes the TLR4-mediated signaling activation through its E3 ligase domain leading to production of pro-inflammatory cytokines and type I interferon (By similarity). Also plays a negative role in the regulation of exogenous cytosolic DNA virus-triggered immune response. Mechanistically, enhances the 'Lys-48'-linked ubiquitination of STING1 leading to its proteasome-dependent degradation. Mediates the ubiquitination of the SIN3-HDAC chromatin remodeling complex component BRMS1. Modulates NCOA4-mediated ferritinophagy and ferroptosis in glioblastoma cells by ubiquitinating NCOA4, leading to its degradation. (Microbial infection) Promotes Zika virus replication by mediating envelope protein E ubiquitination.
Synonyms: GNIP; RNF90
Tractability: Small molecule: a structure with a bound ligand is known. PROTAC: UniProt records ubiquitination sites on it; ubiquitination databases record sites on it.
Gene: Protein-coding gene on chromosome 5 (181,193,924 to 181,205,293, reverse strand). Ensembl gene ENSG00000146054.
Subcellular location: Nucleus; Cytoplasm; Golgi apparatus
Subcellular location (Human Protein Atlas): Vesicles; Cytosol; Nucleoplasm
Gene Ontology:
Molecular function: protein binding; ubiquitin protein ligase activity; zinc ion binding
Biological process: antiviral innate immune response; innate immune response; protein ubiquitination
Cellular component: cytoplasm; Golgi apparatus; nucleus
Genetic constraint (gnomAD): Loss-of-function variants: 29 observed, 26.56 expected, observed/expected ratio (o/e) 1.09, 90% interval 0.81 to 1.49. The synonymous counts are far from expectation, so gnomAD's model fits this gene poorly and the ratio says little. Missense variants: 706 observed, 553.4 expected, observed/expected ratio (o/e) 1.28, 90% interval 1.2 to 1.36. Synonymous variants: 328 observed, 251.72 expected, observed/expected ratio (o/e) 1.3, 90% interval 1.19 to 1.43.
Homologues: Orthologues: chimpanzee TRIM7 (99% identical), macaque TRIM7 (97% identical), rabbit TRIM7 (91% identical), pig TRIM7 (90% identical), mouse Trim7 (89% identical), dog TRIM7 (88% identical), rat Trim7 (87% identical), guinea pig TRIM7 (55% identical). Paralogues in human: TRIM27 (34% identical), TRIM58 (33% identical), TRIM39 (32% identical), TRIM41 (32% identical), TRIM11 (32% identical), TRIM21 (31% identical), TRIM4 (29% identical), TRIM69 (29% identical), TRIM17 (29% identical), TRIM26 (29% identical), TRIM10 (28% identical), TRIM15 (26% identical), and 68 more.
Diseases named in the same sentence as TRIM7 in open-access papers:
TRIM7 is named in the same sentence as 26 diseases in open-access papers, as found by Europe PMC text mining. Sharing a sentence is not in itself a finding about the gene and the disease. The quoted sentences say what the papers report.
osteosarcoma (10 papers, 2021 to 2025). A usually aggressive malignant bone-forming mesenchymal neoplasm, predominantly affecting adolescents and young adults. "Research has shown that TRIM7 is highly expressed in osteosarcoma tissues and is an independent risk factor predicting poor prognosis." (PMID 39062505, 2024). "Moreover, elevated levels of TRIM7 in osteosarcoma cells are closely associated with tumor chemoresistance." (PMID 39062505, 2024). "Loss of N6-Methyladenosine modification of TRIM7 promoter was observed in osteosarcoma tissues." (PMID 35356464, 2022). "In a previous study, TRIM7 was reported to regulate the tumorigenesis and chemoresistance in osteosarcoma through BRMS1 ubiquitination." (PMID 38509147, 2024). "As an E3 ubiquitin ligase, TRIM7 is highly expressed in certain malignancies, which promotes the proliferation of cancer cells, such as osteosarcoma and glioblastoma." (PMID 38509147, 2024). "It was observed that samples from osteosarcoma patients showed reduced m6A modification of TRIM7 mRNA, thereby increasing the levels of TRIM7 protein and its pro-tumoral functions." (PMID 39205259, 2024). "TRIM7 is upregulated in osteosarcoma tissues, promotes osteosarcoma cell migration and invasion by mediating the ubiquitination of breast cancer metastasis inhibitor 1 (BRMS1), and contributes to chemotherapy resistance." (PMID 36249749, 2022). "METTL3 and METTL14 decrease the RNA level of tripartite motif 7 (TRIM7), while the upregulation of TRIM7 can increase metastasis and the chemoresistance of osteosarcoma by regulating ubiquitination of breast cancer metastasis suppressor 1 (BRMS1)." (PMID 34094986, 2021). "YTHDF2 can directly bind to the 3’-UTR of TRIM7 mRNA and negatively regulate the expression of TRIM7 in osteosarcoma HOS and MG63 cells." (PMID 34094986, 2021). "In addition, METTL3‐ and METTL14‐mediated m6A modifications of TRIM7 regulate osteosarcoma metastasis and chemoresistance." (PMID 39924638, 2025). "Mechanistically, TRIM7 directly binds to breast cancer metastasis suppressor 1 (BRMS1) and promotes its ubiquitination and degradation, positively regulating the migration and invasion of osteosarcoma cells." (PMID 39062505, 2024).
viral infection (6 papers, 2020 to 2025). "Of special interest is that most of these RNAs had not been reported in lung cancers and two genes (HORMAD2 and TRIM7) might associate with virus infection." (PMID 35356464, 2022). "The deregulation and methylation levels of HORMAD2 and TRIM7 in recurrent LUSC tissues might provide references for exploring the potential association of LUSC prognosis with virus infection." (PMID 35356464, 2022). "Here, we discuss the multiple functions of TRIM7 during viral infections and its potential as a therapeutic target." (PMID 39205259, 2024). "In this work, we will focus on the E3-Ub ligase TRIM7 and discuss its dual roles during viral infections and its potential as a therapeutic target." (PMID 39205259, 2024). "TRIM7 has been demonstrated to have significant roles in promoting host defense against viral infections and regulating immune signaling pathways." (PMID 37719674, 2023). "In this review, we aim to provide a comprehensive summary of these findings and emphasize the intricate role of TRIM7 in virus infection and innate immunity." (PMID 37719674, 2023). "A comprehensive understanding of the interaction between TRIM7 and antiviral immunity is crucial for the development of innovative treatments for viral diseases." (PMID 37719674, 2023). "TRIM7 can either promote virus pathogenesis or protect against infection, depending on the context of virus infection." (PMID 35356464, 2022). "The E3 ubiquitin ligase TRIM7 is known to have dual roles during viral infections." (PMID 39205259, 2024). "TRIM7 is an E3-Ub ligase that can either promote or inhibit virus infection." (PMID 37719674, 2023). "A growing body of evidence has also shown that TRIM7 can, in some cases, ubiquitinate viral proteins to promote viral replication and pathogenesis, while in other cases it can promote degradation of viral proteins through the proteasome, reducing virus infection." (PMID 39205259, 2024). "Moreover, TRIM7 may even facilitate viral infection by ubiquitinating viral proteins, including envelope proteins that are critical for tissue and species tropism." (PMID 37719674, 2023). "Additionally, it is possible that TRIM7 may not interact with SARS-CoV-2 during live virus infection or that the degradation of SARS-CoV-2 proteins by TRIM7 may not sufficiently impact virus replication." (PMID 37719674, 2023).
lung carcinoma (5 papers, 2019 to 2024). "The expression of TRIM7 is diminished in tumor tissues compared to adjacent normal tissues, and its level is negatively correlated with the clinical stage of lung cancer." (PMID 38791918, 2024). "Previous studies have shown that TRIM7 can promote lung cancer development and a knockdown of TRIM7 reduced tumor growth." (PMID 31126132, 2019). "TRIM7 negatively regulates the NF-kappa B signaling pathway in lung cancer by degrading p65." (PMID 38791918, 2024). "However, in the Ras-driven lung cancer model, transgenic overexpression of the Trim7 gene increases the tumor size, while TRIM7 protein deficiency leads to a decrease in tumor growth." (PMID 32882786, 2020). "Besides, a clinical study showed a decrease of Trim7 mRNA expression comparing adjacent normal cells in patients with lung cancer." (PMID 32882786, 2020). "TRIM7 was also shown to induce cancer progression in lung cancer cells by promoting the degradation of 14-3-3 ζ (a negative regulator of Vsp34) to trigger autophagy." (PMID 39205259, 2024). "Additionally, TRIM7 can interact with Beclin-1 and LC3B to induce the formation of the autophagosomes and promote autophagy, which can lead to the proliferation and migration of lung cancer cells." (PMID 39205259, 2024).
atherosclerosis (4 papers, 2021 to 2024). A disease characterized by the build-up of fatty material and calcium deposition in the arterial wall resulting in partial or complete occlusion of the arterial lumen. "The E3 ligase TRIM7 promotes the proliferation and migration of VSMCs in atherosclerosis, and the downregulation of TRIM7 alleviates atherosclerosis in ApoE−/− mice." (PMID 38778460, 2024). "Consistent with our results, another TRIM member, TRIM7, is increased in atherosclerosis, and interference of TRIM7 in the same high-fat diet ApoE-/- model effectively mitigated atherosclerosis progression in a recently reported study." (PMID 36229750, 2023). "A growing body of evidence indicates that TRIM7 plays an important role in cancer development, viral pathogenesis, and atherosclerosis and, thus, represents a potential therapeutic target." (PMID 33989636, 2021). "Future investigations are required to study whether TRIM64 and TRIM7 work together in atherosclerosis development." (PMID 36229750, 2023). "In addition to enhancing the activity of GN1, TRIM7 has E3 ubiquitin ligase activity, and through this function, it participates in several processes including glycogen accumulation, cancer development, regulation of atherosclerosis, and of the toll-like receptor 4–mediated innate response." (PMID 33989636, 2021).
glioblastoma (4 papers, 2023 to 2024). The most malignant astrocytic tumor (WHO grade IV). "In contrast, tripartite motif-containing protein 7 (TRIM7) directly binds to and ubiquitinates NCOA4 in a K48-linked polyubiquitylation manner, facilitating the degradation of NCOA4 and reducing the ferritinophagy and ferroptosis of human glioblastoma cells." (PMID 37497000, 2023). "Glioblastoma: Overexpression of TRIM7 inhibits NCOA4-mediated ferritinophagy and ferroptosis through directly binding and ubiquitinating NCOA4 in human glioblastoma cells." (PMID 38072908, 2023). "TRIM7 modulates NCOA4-mediated ferritinophagy and ferroptosis in glioblastoma cells." (PMID 39193375, 2024).
hepatocellular carcinoma (4 papers, 2021 to 2024). A malignant tumor that arises from hepatocytes. "The tripartite motif-containing 7 (TRIM7) gene is a tumor suppressor gene that encodes glycogenin-interacting proteins and an E3 ubiquitin ligase, which suppresses the progression of hepatocellular carcinoma." (PMID 35356464, 2022). "The E3 ligase tripartite motif protein 7 (TRIM7) can directly interact with the tyrosine kinase Src, induce the ubiquitination of Lys48-linked Src, reduce the abundance of the Src protein in hepatocellular carcinoma cells, and inhibit the progression of hepatocellular carcinoma." (PMID 39048965, 2024). "In other cancers, TRIM7 can suppress hepatocellular carcinoma progression, while an oncogenic function was reported in colorectal cancer and pancreatic cancer for TRIM2 and in hepatocellular carcinoma for TRIM52-AS1." (PMID 35928444, 2022). "Moreover, increased TRIM7 expression levels that correlate with tumor size have been described in hepatocellular carcinoma patients, an effect that is related to the regulation of the p38 MAP-kinase pathway." (PMID 33989636, 2021). "However, new evidences also describe TRIM7 as a suppressor of hepatocellular carcinoma progression via inhibition of the Src-mTORC1-S6K1 axis." (PMID 33989636, 2021).
gastric cancer (3 papers, 2024). A primary or metastatic malignant neoplasm involving the stomach. "A reduced level of TRIM7 was observed in human gastric cancer tissues, and its overexpression was associated with prolonged patient survival rates." (PMID 39768197, 2024). "The induction of ferroptosis occurs by the K48 ubiquitination and subsequent degradation of the solute carrier family 7 member 11 (SLC7A11), and is a particularly intriguing aspect of TRIM7’s role in gastric cancer cells." (PMID 39205259, 2024). "Conversely, other studies have demonstrated that TRIM7 is downregulated in samples from gastric cancer (GC) patients." (PMID 39205259, 2024). "However, the role of TRIM7 in gastric cancer (GC) is still undefined." (PMID 38509147, 2024).
non-small cell lung carcinoma (3 papers, 2015 to 2022). A group of at least three distinct histological types of lung cancer, including non-small cell squamous cell carcinoma, adenocarcinoma, and large cell carcinoma. "In non-small cell lung cancer cells, TRIM7 interacts with p65, thereby promoting its ubiquitin-mediated degradation, and therefore TRIM7 regulates NF-κB signaling." (PMID 34769401, 2021). "Comparing with TRIM7, we found an interesting phenomenon that compared with normal human lung epithelial cells (BEAS-2B), the protein level of GNIP1 was obviously upregulated in NSCLC cells, and the expression of GNIP1 in non-small cell lung cancer tissues was increased." (PMID 36042481, 2022).
Flavivirus Infections (1 paper, 2025). Infections with viruses of the genus FLAVIVIRUS, family FLAVIVIRIDAE. "TRIM7 was hypothesized as the likely E3 ligase responsible for envelope ubiquitination from an earlier genome-wide siRNA knockdown screen identifying TRIM7 as a proviral host factor for YFV and from its known expression in tissues relevant for flavivirus infection like the brain." (PMID 40285004, 2025).
gastrointestinal infection (1 paper, 2025). "Taken together, these data suggest that Trim7 has no impact on gastrointestinal infection and persistence by MNVCR6, nor does Trim7 deficiency enable a new tissue niche at persistent time points." (PMID 40464581, 2025).
hyperuricemia (1 paper, 2017). An abnormally high level of uric acid. "We have now shown that rs116911833 [G/A (T80M)] of TRIM7 was significantly associated with hyperuricemia, with the minor A allele representing a risk factor for this condition." (PMID 28410202, 2017). "We also identified rs188780113 [G/A (R478C)] of ATG2A as a novel determinant of the serum concentration of uric acid as well as rs115445569 of ACOT11, rs116911833 of TRIM7, and rs60854092 of NOTCH2 as potential novel susceptibility loci for hyperuricemia." (PMID 28410202, 2017). "The remaining four genes (ATG2A, ACOT11, TRIM7, and NOTCH2) may be novel loci that influence the serum concentration of uric acid or confer susceptibility to hyperuricemia." (PMID 28410202, 2017). "Three SNPs (rs115445569 of ACOT11, rs116911833 of TRIM7, rs60854092 of NOTCH2) were related (P < 0.05 in at least one genetic model) to hyperuricemia, although there was no SNP significantly [P < 3.57 × 10−4 (0.05/140)] associated with this condition." (PMID 28410202, 2017). "In addition, rs115445569 [C/T (R64Q)] of ACOT11, rs116911833 [G/A (T80M)] of TRIM7, and rs60854092 [T/A (F1689I) of NOTCH2 were related to hyperuricemia, although the genotypes of these SNPs were not related to the serum concentration of uric acid." (PMID 28410202, 2017).
kidney cancer (1 paper, 2025). Primary or metastatic malignant neoplasm involving the kidney. "TRIM7, TRIM13, and TRIM26 regulate the PI3K/AKT/mTOR pathway as tumor suppressors in kidney cancers." (PMID 40723250, 2025).
liver cancer (1 paper, 2022). An epithelial or non-epithelial malignant neoplasm that arises from the liver. "TRIM7 ubiquitination degrades Src and inhibits liver cancer progression." (PMID 35064108, 2022).
melanoma (1 paper, 2020). A malignant, usually aggressive tumor composed of atypical, neoplastic melanocytes. "In the GEPIA database, TRIM2 and TRIM27 expression were significantly higher, and TRIM7 and TRIM29 expression was significantly downregulated in melanoma; these results were consistent with data from the Oncomine database (all p < 0.05)." (PMID 33118318, 2020). "The gene expression of TRIM2 and TRIM27 was markedly higher, and the expression of TRIM7, TRIM8, and TRIM29 was significantly downregulated in melanoma." (PMID 33118318, 2020). "Expression of TRIM7 and TRIM29 was mostly low in metastatic melanoma, as represented in blue in the figure, and mostly high in primary melanoma, represented in red." (PMID 33118318, 2020). "We used the GEPIA database to investigate the prognostic analysis of TRIM2, TRIM7, TRIM8, TRIM18 (MID1), TRIM19 (PML), TRIM27, and TRIM29 in melanoma." (PMID 33118318, 2020). "Differential expression of TRIM2, TRIM7, TRIM8, TRIM18 (MID1), TRIM19 (PML), TRIM27, and TRIM29 may play an important role in the development of melanoma." (PMID 33118318, 2020). "TRIM7/8/29 were less frequently expressed in melanoma than in normal tissue." (PMID 33118318, 2020). "TRIM7 and TRIM29 were highly expressed in melanocytes in normal skin tissues but were not detectable in melanoma." (PMID 33118318, 2020).